GFAP (glial fibrillary acidic protein)
Diseases named in the same sentence as GFAP in open-access papers (continued):
Sharing a sentence is not in itself a finding about the gene and the disease.
glioblastoma (continued). "Also, the HBA signal in the cerebral blood vessels away from the glioblastoma region formed a cluster separate from the cluster of GFAP signals." (PMID 32238824, 2020). "GFAP was high in the tumour regions of all glioblastoma samples." (PMID 32238824, 2020). "Furthermore, IMS of Histone H2A, Histone H4, Histone H2B, Tubulin α-1A, and GFAP were obtained in the glioblastoma tissues (sample 2–4)." (PMID 32238824, 2020). "However, in glioblastoma in sample 3, H2A, H4, Tubulin β-2A, Tubulin α-1A, and GFAP show more stable higher intensities than in the normal region, suggesting a difference between metastatic lung tumors and glioblastoma." (PMID 32238824, 2020). "In this way, based on this IMS-HCA data, the distribution similarity of Histone H2A, Tubulin α-1A, and GFAP may suggest the correlation of the first two proteins in glioblastoma development or progression." (PMID 32238824, 2020). "Finally, the intriguing observation that glioblastoma secreted EVs are enriched for GFAP and Tau suggests an interesting biology that warrants further exploration." (PMID 31311947, 2019). "Our findings support this hypothesis and provide proof-of-principle data for DEP microarray and on-chip immunofluorescence analysis of EV-contained GFAP and Tau as a potential glioblastoma detection platform." (PMID 31311947, 2019). "Glioblastoma cell lines secrete EVs enriched for GFAP and Tau." (PMID 31311947, 2019). "Glioblastoma stem cell cultures, shifted for 15 days in serum-containing medium, undergo astrocytic and/or neural differentiation (i.e., increased expression of GFAP and MAP-2) representing an in vitro model of the bulk of heterogeneous non-stem cells in GBM mass." (PMID 30186163, 2018). "Conversely, treatment of GSCs with iloprost resulted in a significant increase in expression of the GSC marker Sox2, and an associated decrease in expression of the differentiation markers, GFAP and β-tubulin, in multiple GSCs and the U87 glioblastoma cell line." (PMID 29137258, 2017). "We also analyzed the expression of GFAP, a protein expressed by glioblastoma and neural stem cells." (PMID 25885700, 2015). "We also evaluated the basal energy metabolism and neurological alterations (expressed as changes in motor activity), and finally, we made a postmortem analysis to measure the glioblastoma biomarker GFAP to assess the BBB integrity and to determine the content of Gln and Glu in the tumours." (PMID 26116110, 2014). "Thus, a gradual release of GFAP in to the blood stream appears plausible in glioblastoma, in contrast to other brain tumors such as metastases." (PMID 23626774, 2013). "Considering the facts presented above, a population of glioblastoma cells identified in this study resembles GFAP+NNP in terms of their multilineage phenotype before differentiation, and the capacity, at least to some degree, for neural and mesenchymal differentiation." (PMID 19216795, 2009). "The multilineage phenotype of cultured glioblastoma cells may represent a stabilized phenotype that is temporarily expressed by normal uncommitted multipotent cells such as GFAP+NNP, and lost after differentiation." (PMID 19216795, 2009). "One study reported a sensitivity of 100% at a specificity of 86% for identifying primary glioblastoma multiforme (GBM) from metastatic carcinoma using immunohistochemical staining for glial fibrillary acidic protein (GFAP), but a significant number of the metastatic cancers are also stained." (PMID 18624795, 2009). "Moreover, the cells derived from a majority of glioblastomas (7 out of 8), as well as GFAP+NNP, showed features of mesenchymal differentiation when exposed to medium with serum." (PMID 19216795, 2009). "The data presented in this review indicate that GFAP-positive (GFAP+) EVs possess broad clinical relevance in both acute and chronic pathologies of the nervous system, including ischemic stroke, traumatic brain injury, glioblastoma, and potentially diabetic and drug-induced polyneuropathy." (PMID 42193441, 2026).
glioblastoma (continued). "Indeed, GFAP-positive cells accounted for the majority of the glioblastoma-forming cells." (PMID 36662405, 2023). "However, by lowering this threshold, for example, to the current analytical sensitivity and suggested cut-off for glioblastomas (0.08 ng ml−1), it may be possible to use serum GFAP for early detection of GBMs." (PMID 35919979, 2022). "The results revealed that GFAP was significantly elevated in the plasma and serum in glioblastoma (GBM) patients." (PMID 36081550, 2022). "Finally, the case is also interesting from a neuropathological point of view since the primary tumor did not present with a GFAP loss, but (already) had a distinct methylation pattern matching glioblastomas with a primitive neuronal component." (PMID 36414742, 2022). "Moreover, we demonstrated that a glioblastoma cell line with a high level of GFAP expression could be eliminated on day 7 of GCV treatment." (PMID 34370752, 2021). "Therefore, the aims of this study were to establish a recombinant plasmid vector bearing the HSVtk/GCV suicide system driven by a GFAP promoter to ablate GFAP-positive tumor cell lines selectively, and to characterize the possible neural differentiation of glioblastoma under GCV challenge." (PMID 34370752, 2021). "Interestingly, the immunohistochemical findings of glial fibrillary acidic protein (GFAP) indicated the characteristic of metastatic glioblastoma, despite that the histopathological findings of Hematoxylin & Eosin (H&E) staining was suspicious of osteoclastoma." (PMID 32736607, 2020). "Tumours were then analysed for the presence of classical hallmarks of human glioblastoma multiforme (GBM) such as pleomorphic GFAP+ glial cells, mitoses, diffuse infiltrative growth, pseudopalisading microscopic necrosis and microvascular proliferation." (PMID 26899176, 2016). "Histopathology confirmed glioblastoma IDH-wildtype CNS WHO grade 4 with immunohistochemistry, showing glial fibrillary acidic protein marker and ATRX positivity but IDH-1 R132H negativity." (PMID 40282523, 2025). "On the contrary to Gli-55, Gli-35 have shown increased selective binding to glioblastoma cells (Gli-55 binds also to glial fibrillary acidic protein), fixation dynamics and GBM uptake, thus it could be a better imagistic and GBM drug delivery system." (PMID 41012445, 2025). "Given the role of GFAP‐expressing cells in promoting ECM degradation and angiogenesis, glioblastoma tissues were immunostained with a panGFAP antibody." (PMID 40971724, 2025). "In the co-treatment of glioblastoma cells with human astrocytes using TMZ and Bay 11-7082 (a NF-κB inhibitor), the expression levels of GFAP, waveform protein, Notch1, and survivin were significantly reduced." (PMID 38672496, 2024). "Our findings revealed elevated levels of Notch1, CD133, and Nestin expression in glioblastomas from the GFAP-Cre; KrasG12D; APCL/+; p53L/L mice when compared to brain sections from the GFAP-Cre;KrasG12D;p53L/L group." (PMID 38473403, 2024). "The GFAP-TVA-dependent glial cell-specific Nf1 (neurofibromin) inactivation, along with K-RasG12V expression, triggers the growth of the most aggressive glioblastoma subtype (MES), exhibiting mesenchymal features." (PMID 37176013, 2023). "Immunohistochemistry results indicated that GFAP, S-100, Olig-2, and ATRX were positive in more than 90% of glioblastomas." (PMID 37483487, 2023). "DAPI + and GFAP + /DAPI + cells were quantified for U251 cells and primary human glioblastoma cultures, respectively." (PMID 37225786, 2023). "The capability for neural differentiation in stable glioblastoma clones during GCV treatment was assessed by performing immunocytochemistry for nestin, GFAP, and βIII-tubulin." (PMID 34370752, 2021). "In contrast, GFAP level was increased by high-dose FAD challenge, suggesting that FAD disrupts the homeostasis of glioblastoma stem-like cells and promotes differentiation." (PMID 30388862, 2018).
glioblastoma (continued). "Double-immunofluorescence stainings in glioblastomas revealed co-expression of JAM-A with CD133, SOX2, nestin, and GFAP in tumor cells as well as some co-expression with the microglial/macrophage marker IBA-1." (PMID 28677106, 2017). "Furthermore, in GBM glioblastoma cells, CA promoted apoptosis by inducing cell cycle arrest and degradation of cyclin B1, RB, SOx2 and GFAP, molecules involved in cell survival and maturation processes." (PMID 27869665, 2016). "Quantitative analysis of tumour incidence, tumour size, proliferation index, and vessel density as well as semiquantitative analysis of GFAP- and VEGF expression after chemotherapy of 101/8 rat glioblastoma with different formulations of doxorubicin." (PMID 21573151, 2011). "Review of 200 glioblastomas showing that 50% of them contain cells expressing NFP and GFAP supports such a possibility (PV and CDD, unpublished observations)." (PMID 20181261, 2010). "When cultured under serum-starvation conditions, in contrast to GFAP+NNP, glioblastoma cells formed stable aggregates, and aggregate cells maintained the multilineage phenotype for several months (as currently observed for 8 months)." (PMID 19216795, 2009). "In our culture model, a population of glioblastoma cells was able to form aggregates composed of cells with multilineage phenotype, i.e. showing expression of: CD44, Vimentin, GFAP, Nestin, Beta III-tubulin, MAP2, Fibronectin and SOX-2, but not CD133." (PMID 19216795, 2009). "Considering our data, and recent literature demonstrating mesenchymal differentiation of glioblastoma cells, we defined the CD44+, GFAP-, MAP2- population of glioblastoma cells as mesenchymal." (PMID 19216795, 2009). "The co-expression of neuronal and glial markers is transient or stable during the differentiation of GFAP+NNP and glioblastoma cells, respectively." (PMID 19216795, 2009). "In contrast to GFAP+NNP, an efficient differentiation arrest was observed in all cell lines isolated from glioblastomas." (PMID 19216795, 2009). "The GFAP-Cre; KrasG12D; APCL/+; P53L/L mouse model demonstrates an increased activation of the WNT/β-catenin pathway and exhibits cancer-stem-cell-like properties, closely resembling human glioblastoma multiforme’s histopathological features." (PMID 38473403, 2024). "In another investigation, isolated peripheral mononuclear cells were used to detect glioblastoma CTCs using GFAP." (PMID 37568620, 2023). "While the tumor cells of the pre-existing glioblastoma had stained positive for glial fibrillary acidic protein (GFAP), the immunohistochemical reaction for GFAP now remained negative." (PMID 36414742, 2022). "Strongly glial fibrillary acidic protein (GFAP) positive astrocytes surrounding calcifications express podoplanin, a protein strongly expressed by a subset of reactive astrocytes in glioblastoma, and after ischemic and stab wound injuries." (PMID 35309892, 2022).
glioblastoma (continued). "Glial fibrillary acidic protein (GFAP) is widely expressed in astroglial and neural stem cells in the brain, and it also serves as a major marker in immunohistology of astroglial tumors, such as glioblastomas." (PMID 34771592, 2021). "Glioblastoma patients with >20% glial fibrillary acidic protein+CD16+ non-classical monocytes had a significantly shorter median overall survival (8.1 versus 12.1 months)." (PMID 33501422, 2021). "We did observe that GFAP was all positive in U-87 and C6 glioblastoma cells and Ki67 (a marker of proliferation) was all negative in N/G mixed cells." (PMID 33162824, 2020). "Interestingly, the immunohistochemical findings of GFAP were positive in bone specimens, which substantiated the diagnosis of ECM from glioblastoma." (PMID 32736607, 2020). "While GFAP and Tau are highly abundant in EVs derived from glioblastoma cell lines, they are unlikely to be specific biomarkers of glioblastoma." (PMID 31311947, 2019). "Here we tested this platform to detect EV-contained glial fibrillary acidic protein (GFAP) and Tau in patients with and without a diagnosis of glioblastoma." (PMID 31311947, 2019). "We then performed immunohistochemical labelling on specimens from 43 glioblastoma patients with de-novo and recurrent glioblastoma to validate the presence of CD274+ astrocytes in the tumor environment, as well as GFAP and marker genes of various myeloid cell types." (PMID 31186414, 2019). "We did not detect significant differences in GFAP or Tau concentration between patients with meningioma, brain metastasis, or glioblastoma." (PMID 31311947, 2019). "Using an on-chip DEP-IF platform, we showed that the concentration of GFAP and Tau in EVs isolated from the plasma of glioblastoma patients is higher than in patients without history of brain cancer." (PMID 31311947, 2019). "Astrocytes stained with glial fibrillary acidic protein (GFAP) were more abundant in glioblastomas (GBM) than in normal brain tissue." (PMID 26976322, 2016). "Two CD150 negative glioblastoma cases were characterized by high levels of nestin and GFAP expression." (PMID 25710480, 2015). "GFAP was found elevated in the plasma of patients with glioblastoma, whereas other intracranial tumors including metastases were not shown to increase GFAP blood levels." (PMID 23626774, 2013). "However, in GFAP+NNP this phenotype was observed only temporarily prior to differentiation into neural cells, whereas it was very stable in glioblastoma cells." (PMID 19216795, 2009). "However, in contrast to GFAP+NNP, glioblastoma cells with multilineage phenotype appeared to be very resistant to our neural differentiation medium." (PMID 19216795, 2009). "Nevertheless, a subpopulation of cells isolated from four glioblastomas differentiated after serum-starvation with varying efficiency into derivatives indistinguishable from the neural derivatives of GFAP+NNP." (PMID 19216795, 2009). "Although features of variable differentiation in glioblastoma cell cultures have been reported, a comparative analysis of differentiation properties of normal neural GFAP positive progenitors, and those shown by glioblastoma cells, has not been performed." (PMID 19216795, 2009). "The pathological results of the two patients indicated that they had glioblastoma (GBM) and WHO grade II (LGG), and cells were identified by GFAP immunofluorescence (Fig. SA)." (PMID 37069338, 2023). "Compared with normal tissue, the higher expression of GFAP in LGG and glioblastoma (GBM) suggested a tendency of astrocyte segregation toward tumor lesion." (PMID 34540693, 2021). "Although these expression differences are not statistically significant due to the small group size, GFAP low expressing group could be excluded for functional analyses on glioblastoma cell lines based on these findings." (PMID 33251771, 2021).
glioblastoma (continued). "This study moreover underlined that infection of as few as 60 GFAP-expressing cells in the V-SVZ was sufficient to induce the emergence of a full-blown tumor containing GSCs whereas glioblastoma rarely developed when GFAP-expressing non-stem cells from the cortex were transduced." (PMID 33281564, 2020). "To determine the diagnostic value of the discrimination threshold established in our exploratory cohort (Tau > 2.6 rIF and GFAP > 1.7 rIF), we analyzed prospectively collected plasma from a cohort of 15 glioblastoma patients and 8 control subjects without history of brain tumor." (PMID 31311947, 2019). "On the other hand, the level of glial fibrillary acidic protein (GFAP), a marker of differentiated astrocyte, was upregulated upon differentiation condition, suggesting that cancer stem-like cell populations in U373 glioblastoma have morphological and molecular characteristics of cancer stem cells." (PMID 30388862, 2018). "Moreover, in a GFAP-CreER; PtenloxP/loxP; Trp53loxP/loxP; Rb1loxP/loxP; Rbl1−/− GEMM model of glioblastoma where tumor can spontaneously arise in different regions of the cerebrum, tumors that arose near the SVZ were more likely to be of proneural subtype (p < 0.0001)." (PMID 27056901, 2016). "In a GFAP-CreER; PtenloxP/loxP; Trp53loxP/loxP; Rb1loxP/loxP; Rbl1−/− Genetically Modified Murine Model (GEMM) of glioblastoma where tumor can spontaneously arise in different regions of the cerebrum, glioblastoma that arose near the SVZ were more likely to be of proneural subtype." (PMID 27056901, 2016). "Glioblastoma cells treated with the DNA demethylation agent 5-azacytidine over 28 days of astrocyte-induced differentiation demethylated exon 2 of POLGA leading to increased mtDNA copy number and expression of the astrocyte endpoint marker glial fibrillary acidic protein (GFAP)." (PMID 25719248, 2015). "Moreover, EBF1+ cells did not express GFAP, a well-recognized marker of glioblastoma." (PMID 34272603, 2021). "Moreover, using the SNB-19 line of glioblastoma origin, we found CD49f present on glial fibrillary acidic protein (GFAP)-positive cells, while CD200 was not co-expressed with this glial marker, in contrast to its close correlation with the other neural markers analyzed." (PMID 23826393, 2013). "Furthermore, immunofluorescence staining of tumor tissues in the GBM rat brain confirmed the high expression of integrin αvβ3, tumor angiogenesis marker CD31 and astrocyte activation marker GFAP in glioblastoma region, with low expression observed in healthy brain tissue." (PMID 38647690, 2024). "Therefore, GFAP may be important for diagnosing TBI and other pathologies, intracerebral hemorrhage, or neoplastic diseases, such as glioblastoma multiforme (GBM), are a few examples." (PMID 37630021, 2023). "The traditional glioblastoma prognostic markers GFAP, S100, OLIG2, MAP2 and SYN were also analyzed and found to be indistinguishable among the intracranial glioblastoma xenografts." (PMID 25955030, 2015). "Apart from what was already known (i.e., elevated GFAP values in ICH, traumatic brain injury, and glioblastoma), we were not able to identify a disease or a group of diseases in our widespread explorative study that was consistently associated with increased blood GFAP levels." (PMID 23626774, 2013). "In addition, our results show that one out of eight glioblastomas (GBM7) did not form aggregates and did not differentiate in accordance with the GFAP+NNP differentiation model." (PMID 19216795, 2009).